BCL9L (BCL9 like)
Diseases named in the same sentence as BCL9L in open-access papers (continued):
Sharing a sentence is not in itself a finding about the gene and the disease.
Sepsis (1 paper, 2023). Sepsis is defined as life-threatening organ dysfunction caused by a dysregulated host response to infection. "There is currently limited literature about the relationship between BCL9L and sepsis." (PMID 36918563, 2023). "BCL9L, BCL11B, CD247, CD96 and SAMD3 were decreased in sepsis and mainly expressed in the T cell; while MAFG increased in sepsis and localizes to monocytes." (PMID 36918563, 2023). "The expression results of core genes in different samples showed that five genes (BCL9L, BCL11B, CD96, SAMD3 and CD247) were decreased in sepsis samples, compared with the normal group." (PMID 36918563, 2023).
Solid Pseudopapillary Neoplasm of the Pancreas (1 paper, 2016). A low-grade malignant neoplasm that arises from the exocrine pancreas. "Eighteen cases of solid pseudopapillary neoplasms of the pancreas were evaluated for RNA expression levels of FLI1, DKK1, INPP5D (SHIP1), IGFBP3, PBK (TOPK), and BCL9 and BCL9L." (PMID 27539223, 2016).
cancer (38 papers, 2010 to 2025). A tumor composed of atypical neoplastic, often pleomorphic cells that invade other tissues. "We found that ac4C peaks in the genes associated with the cancer pathway (BCL9L), the cell cycle (AKT1) and stem cell maintenance (SOX4) decreased in the NAT10 knockdown UMUC‐3 cells." (PMID 35522942, 2022). "Caspase 2 deficiency results in the predisposition of cancer cells to aneuploidy, due to B-cell CLL/lymphoma 9-like (BCL9L) protein dysfunction." (PMID 36430734, 2022). "It has been well demonstrated by some studies that BCL9L is overexpressed in several cancer types and is associated with tumour progression." (PMID 35628130, 2022). "Intrinsic mechanical properties and BCL9L expression in tumor cells determine their stemness and are linked to cancer progression." (PMID 33274785, 2021). "Thus, our findings offer some insights into enhancing the susceptibility of tumors with high BCL9/BCL9L expression to cancer immunotherapy." (PMID 38811552, 2024). "One mutation at 3′ UTR could influence the gene expression of BCL9L, providing an additional mechanism for the aberrant expression in cancer." (PMID 35628130, 2022). "A DMR was also identified in the BCL9L gene—an activator of Wnt signaling associated with B cell malignancies that have been implicated in cancer development and epithelial-mesenchymal transition through a down-regulation of c-Myc, cyclin D1, CD44, and vascular growth factor in tumor cells." (PMID 34502260, 2021). "As previous studies investigating BCL9 and BCL9l (BCL9/9l) were performed in colitis-associated cancer models, we wished to investigate the effect in models of cancer directly driven by activation of Wnt signalling either by Apc gene deletion or β-catenin stabilisation." (PMID 30760720, 2019). "This approach is supported by the important finding that BCL9L has been identified as a biological marker for soft cancer cells, enabling them to be distinguished from their stiff counterparts." (PMID 40277910, 2025). "Suppressing B-cell lymphoma 9 and B-cell lymphoma 9-like (BCL9/BCL9L) inhibits tumor growth and boosts immune responses against cancer." (PMID 38811552, 2024). "Amazingly, our findings uncovered that targeting BCL9/BCL9L can excellently enhance antigen presentation in cancers." (PMID 38811552, 2024). "In dysplastic urothelium of cancer samples, BCL9L was weak to strongly expressed (mean H-score 1.08), apparently stronger expressed, as in non-dysplastic urothelium, especially in the higher grade dysplastic cells (patient 2, 8)." (PMID 35628130, 2022). "Other in vitro and in vivo studies have proved the oncogenic effect of BCL9L through knockdown and overexpression experiments in other cancer entities." (PMID 35628130, 2022). "They suggested the involvement of BCL9L protein and Wnt/β-catenin signalling in the self-renewal and pluripotent mechanisms of cancer stem cells." (PMID 35628130, 2022). "In general, the oncogenic effect of BCL9L in cancer is also confirmed by other studies for several tumour entities." (PMID 35628130, 2022). "These include the tumour suppressors, PDCD4, RB1, STK2, transcriptional regulators with reported roles in cancer, BCL9L, STAT5B and proteins that are involved in control of the cell cycle, ANAPC4, ANAPC5, RBX1." (PMID 35573784, 2022). "Dysregulation of β-catenin cofactors including the BCL9L protein, alter Wnt/β-catenin signalling in cancer, which can contribute to tumour progression." (PMID 35628130, 2022). "BCL9L protein is overexpressed and correlated with poor prognosis and poor overall survival in various tumour entities, suggesting the role of BCL9L in the cancer’s progression." (PMID 35628130, 2022). "In cancer, BCL9L/BCL9L is overexpressed in several tumour entities and it is associated with the development of tumourigenicity, tumour stage, and cancer progression." (PMID 35628130, 2022).
cancer (continued). "The gene shared most commonly between cancer types, BCL9L, is an oncogene and interacts with m6A patterns in the Wnt signaling pathway." (PMID 33849552, 2021). "More importantly, in our small cohort study, we indeed observed that BCL9L expression is related to the prognosis of patients with cancer." (PMID 33274785, 2021). "To date, the function of BCL9L in cancers mainly attributes to its interaction with β-Catenin and facilitating TCF-mediated transcription, thus activates canonical Wnt signaling and its downstream EMT and stemness related genes." (PMID 33436545, 2021). "For BCL9L, higher expression was observed in tumors of larger size and in HCCs containing cancer cells in nearby lymph nodes." (PMID 31440992, 2020). "Among all candidate genes, we paid specifically attention to BCL9L because it played essential tumor-promoting role in modulation of carcinogenesis and cancer progression." (PMID 33117820, 2020). "Analyses using the miRanda and Pic Tar algorithms indicated that several cancer-associated genes including MMP11, ERBB2, ERBB3, EDN1, VEGF-A, MMP14 and BCL-9L, were potential target genes of miR-125a." (PMID 22768249, 2012). "This hypothesis is supported by the finding that the Wnt signaling protein BCL9L is elevated in the cells of soft cancer cells and modulates their stemness and tumorigenic capacity." (PMID 40277910, 2025). "The role of BCL9L has been wildly studied and focused on in the field of cancer." (PMID 36918563, 2023). "Based on these analyses, we propose that BCL9L might function as a useful marker to predict cancer patient prognosis." (PMID 33274785, 2021). "Efforts to exploit aneuploidy tolerance mechanisms and the BCL9L/caspase-2/BID axis may limit cancer diversity and evolution." (PMID 28073006, 2017). "Targeting BCL9/BCL9L to regulate cDC1 function and directly orchestrate a positive feedback loop necessary for optimal antitumor immunity could serve as a potential strategy to counter immune suppression and enhance cancer immunotherapy." (PMID 38811552, 2024). "We first evaluated whether in fetal‐like HB cell lines, the partial deletion of CTNNB1 exon 4 could alter the capability of β‐catenin to interact with BCL9 and BCL9L, which are established co‐activators of the Wnt pathway important to specify a stem cell‐like phenotype in cancer cells." (PMID 28923827, 2017). "Therefore, our study may also provide a novel mechanism for targeting Wnt/β-catenin signaling to promote antitumor immunity by overcoming cDC1 dysfunction in TME, suggesting that targeting BCL9/BCL9L to improve NF-κB-dependent antigen presentation in tumors is a potential approach to cancer therapy." (PMID 38811552, 2024). "Interestingly, BCL9L protein was increased on average as well as in some subpopulations of cells in MIBC and in dysplastic urothelial cells compared to NMIBC and non-dysplastic urothelium, suggesting an association with BC tumour stage and malignancy of carcinoma cells." (PMID 35628130, 2022). "Here we show, that BCL9L is up-regulated in PDAC cell lines and patient tissue compared to non-cancer controls." (PMID 27713160, 2016). "We demonstrated that targeting BCL9/BCL9L facilitates the antigen presentation and tumor infiltration of cDC1, as well as boosts the tumor infiltration of CD8+ T cells, thereby improving the responses to cancer immunotherapy." (PMID 38811552, 2024). "Understanding aneuploidy tolerance mechanisms more widely, and the BCL9L/caspase-2/BID axis specifically, may unravel potential vulnerabilities in aneuploid cancers, which could be exploited to limit intercellular heterogeneity, a substrate for selection and tumor evolution." (PMID 28073006, 2017).
cancer (continued). "However, the relevance of BCL9L expression for the integrity of adherens junctions in cancer cells has not been investigated before." (PMID 27713160, 2016). "For example, silencing BCL9L suppresses EMT and nucleus translocation of β-Catenin in carcinoma cells, while forced expression of BCL9L induces EMT of nontransformed cells." (PMID 33436545, 2021).
tumor (38 papers, 2010 to 2025). "In summary, we successfully identified the CD8+ T cells and cDC1 populations in tumors and TdLNs from B16-OVA tumor-bearing Bcl9/Bcl9l deficiency mice using scRNA-seq." (PMID 38811552, 2024). "For instance, BCL9L positively correlates with tumor invasiveness, migration ability, cell polymorphism, and tumor progression." (PMID 38233930, 2024). "To precisely investigate how BCL9/BCL9L governs the functions of cDC1, we performed single-cell sequencing (scRNA-seq) of tumors and TdLNs from B16-OVA tumor-bearing Bcl9/Bcl9l deficiency mice." (PMID 38811552, 2024). "We found that tumor growth was notably decreased in MC38 tumor-bearing Bcl9/Bcl9l deficiency mice compared with control mice, with a TGI of 65.6%." (PMID 38811552, 2024). "Increased expression of these activation markers on cDC1 was observed in this model, as well as in MC38 tumor-bearing Bcl9/Bcl9l deficiency mice." (PMID 38811552, 2024). "Consistently, positive regulation of T cell proliferation in cDC1 was also upregulated in tumors of B16-OVA tumor-bearing Bcl9/Bcl9l deficiency mice, supporting that cDC1 primed CD8+ T cells." (PMID 38811552, 2024). "We found that XCL1 expression by intratumoral CD8+ T cells was upregulated in hsBCL9z96-treated CT26 tumor-bearing mice and MC38 tumor-bearing Bcl9/Bcl9l deficiency mice." (PMID 38811552, 2024). "To investigate this, we assessed the expression of Rel, Relb and Irf1 of cDC1 in TdLNs and tumors from B16-OVA tumor-bearing Bcl9/Bcl9l deficiency mice using SCENIC analysis." (PMID 38811552, 2024). "The frequency of OVA257-264-specific CD8+ T cells was increased in TILs from MC38-OVA tumor-bearing Bcl9/Bcl9l deficiency mice compared to the control." (PMID 38811552, 2024). "To further investigate how BCL9/BCL9L regulates the functions of cDC1, we explored the transcriptional differences of CD8+ T cells and cDC1 in TdLNs and tumors from B16-OVA tumor-bearing Bcl9/Bcl9l deficiency mice using single-cell transcriptomics analysis." (PMID 38811552, 2024). "Identically, Xcl1 mRNA and XCL1 protein levels were increased markedly in these tumors using qPCR, as well as tumors from MC38 tumor-bearing Bcl9/Bcl9l deficiency mice." (PMID 38811552, 2024). "We analyzed transcriptional changes and signaling enrichment of cDC1 in tumors and TdLNs from B16-OVA tumor-bearing Bcl9/Bcl9l deficiency mice." (PMID 38811552, 2024). "The tumour-associated gene BCL9L, a coactivator of β-catenin, carries frequent mutations in the regulatory 5′ and 3′ UTR regions of mRNA transcript in three patients out of eleven." (PMID 35628130, 2022). "The tumour-associated gene BCL9L, as a coactivator of β-catenin is involved in Wnt/β-catenin signalling, was identified to be exclusively mutated at the 5′ and 3’ UTR of BC patients." (PMID 35628130, 2022). "We have found that the disruption of the interaction of β-catenin with Bcl9/Bcl9L proteins in tumor cells of MMTV-PyMT transgenic mice causes a significant reduction in primary tumor growth and metastasis formation." (PMID 34545187, 2021). "Our BCL9 and/or BCL9L knockdown experiments underline the possible advantageous effect of downregulation of BCL9 proteins on tumor growth control." (PMID 31440992, 2020). "Q713∗ and the splice-site mutation were observed in two of three alleles of tumor samples 379 and 363, respectively, which suggests that BCL9L mutations occurred early, prior to chromosome duplication." (PMID 28073006, 2017). "Similarly, the expression of genes related to antigen processing and presentation such as Tap1, Tap2, B2m, and Psmb9, was also upregulated in tumors from hsBCL9z96-treated CT26 tumor-bearing mice and MC38 tumor-bearing Bcl9/Bcl9l deficiency mice." (PMID 38811552, 2024).
tumor (continued). "Similarly, increased Ifng mRNA and IFN-γ protein levels were observed in tumors from hsBCL9z96-treated CT26 tumor-bearing mice and MC38 tumor-bearing Bcl9/Bcl9l deficiency mice." (PMID 38811552, 2024). "Similar results were also obtained in TdLNs from MC38-OVA tumor-bearing Bcl9/Bcl9l deficiency mice." (PMID 38811552, 2024). "In addition, anti-PD-1 therapy achieved a greater decrease in MC38 tumor growth of Bcl9/Bcl9l deficiency mice than those of Bcl9f/fBcl9lf/f mice as well as increased the survival in Bcl9f/fBcl9lf/f Cre-ERT2 mice (TGI = 92.3%)." (PMID 38811552, 2024). "Importantly, T cell activation was enhanced in tumors and TdLNs from B16-OVA tumor-bearing Bcl9/Bcl9l deficiency mice." (PMID 38811552, 2024). "Furthermore, we demonstrated that TAK1/NF-κB/IRF1 signaling was also activated in cDC1 from TdLNs of MC38 tumor-bearing Bcl9/Bcl9l deficiency mice using multiplex immunofluorescence." (PMID 38811552, 2024). "To investigate this hypothesis, we used Batf3−/− mice and found that increased anti-tumor immunity upon Bcl9/Bcl9l blockade was lost in cDC1-deficiency mice." (PMID 38811552, 2024). "Moreover, we further disclosed the underlying of collagen/ITGB1 induced tumor progression, which was dependent on a BCL9L/β-catenin/BCL2 signaling pathway." (PMID 34319913, 2021). "Thus, the UTR mutations could provide a molecular mechanism for an aberrant expression of tumour-associated genes such as BCL9L." (PMID 35628130, 2022). "Hence, the subtle changes in gene expression may underlie the modulatory role of Bcl9 and Bcl9L on β-catenin-mediated Wnt signaling and tumor progression (see “Discussion”)." (PMID 34545187, 2021). "In BLC, NAT10 promotes tumor growth by upregulating key oncogenes such as B-cell CLL/lymphoma 9-like (BCL9L), SOX4, and AKT1 through ac4C modification." (PMID 41446042, 2025). "We found that cDC1 numbers are increased in tumors from hsBCL9z96-treated CT26 tumor-bearing mice, as well as MC38 tumor-bearing Bcl9/Bcl9l deficiency mice." (PMID 38811552, 2024). "Together, we demonstrate that targeting BCL9/BCL9L plays a crucial role in cDC1-modulated antigen presentation of tumor-derived antigens, as well as CD8+ T cell activation and tumor infiltration." (PMID 38811552, 2024). "CD8+ T cell in vitro proliferation was increased in cross-presentation of CD11c+ DC-CD8+ T cells in both hsBCL9Z96 tumor model and Bcl9/Bcl9l KO tumor model compared with vehicle and wild-type (WT) respectively." (PMID 38811552, 2024). "Here, we show that targeting BCL9/BCL9L enhanced antigen presentation by stimulating cDC1 activation and infiltration into tumor." (PMID 38811552, 2024). "Consistently, the CXCL9 expression by cDC1 and CXCR3 expression by CD8+ T cells were upregulated in tumors from hsBCL9z96-treated CT26 tumor-bearing mice, as well as from MC38 tumor-bearing Bcl9/Bcl9l deficiency mice." (PMID 38811552, 2024). "Pharmacological inhibition of BCL9/BCL9L with a novel inhibitor hsBCL9z96 or Bcl9/Bcl9l knockout mice markedly delayed tumor growth and promoted antitumor CD8+ T cell responses." (PMID 38811552, 2024). "The expression of phospho-TAK1, phospho-NF-κB p65, and IRF1 of intratumoral cDC1 were upregulated from hsBCL9z96-treated CT26 tumor-bearing mice, as well as from MC38 tumor-bearing Bcl9/Bcl9l deficiency mice." (PMID 38811552, 2024). "After that, a group of primary tumor cells acquired six additional mutations (in genes AKT1, BCL9L, B2M, FBXW7, MUTYH, RSPO2)." (PMID 38685065, 2024). "Having established that targeting BCL9/BCL9L facilitates cDC1 activation and tumor infiltration, we next examined how cDC1 contribute to CD8+ T cell responses in tumors after the inhibition of BCL9." (PMID 38811552, 2024). "The mRNA and protein levels of the IFN-γ-induced chemokine CXCL9 were also upregulated in tumors from hsBCL9z96-treated CT26 tumor-bearing mice and MC38 tumor-bearing Bcl9/Bcl9l deficiency mice." (PMID 38811552, 2024).